MMP1 (matrix metallopeptidase 1)
Diseases named in the same sentence as MMP1 in open-access papers (continued):
Sharing a sentence is not in itself a finding about the gene and the disease.
breast carcinoma (continued). "BACH1 is repressed by RKIP, which targets let-7, thereby inhibiting breast cancer bone metastasis by downregulating the expression of BMS genes, including MMP1, OPN, and CXCR4." (PMID 38321558, 2024). "In breast cancer, bioinformatic analysis indicated that BACH1 mediates four Bone Marrow Signature (BMS) genes, including MMP1, CXCR4, FHL1, and DUSP1." (PMID 38321558, 2024). "By comparing gene expression between different sublines of human breast cancer cell line MDA-MB-122, researchers identified four highly overexpressed genes in the bone metastasis group: IL11, CTGF, CXCR4, and MMP-1." (PMID 38041134, 2023). "It was shown that MMP-1 cleaves the PAR1 receptor for activation and generates PAR1-dependent Ca2+ signals in MCF-7 breast cancer cells and promotes tumorigenesis in a xenograft in vivo model." (PMID 37175852, 2023). "In breast cancer, overexpression of CDH3 will increase cell invasion and migration and increase MMP1 and MMP2 expression." (PMID 37151391, 2023). "GPR176 silencing was shown to reduce the expression of MMP1, MMP9, and VEGF, accounting for the effects of GPR176 in promoting the invasion and metastasis of breast cancer cells." (PMID 37079213, 2023). "RANK is also expressed in breast cancer cells, and RANKL promotes the expression of bone metastasis-related genes (such as IL-11, NCF2, PRG-1, MMP-1) in RANK-positive tumor cells." (PMID 38041134, 2023). "Meanwhile, exogenous miR-186-5p mimic in MDA-MB-231 cells significantly inhibited the expression of SBEM, p-PI3K, p-AKT and their downstream pathways, MMP1, MMP3, MMP9, CyclinD1, PCNA and CyclinB1 proteins and reduced proliferation of breast cancer cells." (PMID 37477531, 2023). "BMP-6 inhibited the migration and invasion of breast cancer MDA-MB-231 cells, and this effect was attenuated by overexpression of MMP1." (PMID 36677584, 2023). "This study compared the expression of vimentin, α-SMA, MMP1, PDGF and CD95 in the two types of breast cancer to assess which factors play a greater role in the process of local recurrence in each type of breast cancer." (PMID 38046195, 2023). "In breast cancer patients, expression of the POU class 1 homeobox 1 transcription factor (Pit-1) was positively correlated with the presence of both MMP1 and MMP13." (PMID 36677584, 2023). "Findings also indicate the significant elevation of a matrix metalloproteinase 1 (MMP1) and CD63 complex in the urine of breast cancer patients." (PMID 38250812, 2023). "Accumulating evidence has revealed that MMP1 is usually overexpressed in multiple cancers including lung cancer, esophageal squamous cell carcinoma (ESCC), nasopharyngeal carcinoma, breast cancer, and OSCC." (PMID 36105241, 2022). "For instance, Massaque and colleagues identified 18 genes, including IL13Ra2, SPARC, MMP1, and MMP2, which can lead to breast cancer metastasis to the lungs." (PMID 35045088, 2022). "These three chemokines play essential roles in the development of breast cancer by activating survival proteins, β-strand proteins, mitogen-activated protein kinase phosphatase 1 (MKP-1), and matrix metalloproteinase 1 (MMP-1)." (PMID 36479091, 2022). "Our results indicated that MMP1, CD24, SDC1, and SPP1 are potential novel prognostic biomarkers and candidate immunotherapy targets for breast cancer." (PMID 35037689, 2022). "Overexpression ofCD24, MMP1, SDC1, and SPP1 indicated the poor prognosis in breast carcinoma patients analyzed by Kaplan–Meier (KM) Plotter." (PMID 35037689, 2022). "MMP-1 combined with ADAMTS1 can activate osteoclast differentiation by modulating the bone microenvironment in favor of osteoclastogenesis, to promote breast cancer bone metastasis." (PMID 35359350, 2022). "The expression of CD24, MMP1, SDC1, and SPP1 was much higher in breast carcinoma tissue than in Para cancerous tissues analyzed by Gene Expression Profiling Interactive Analysis (GEPIA) and ONCOMINE." (PMID 35037689, 2022).
breast carcinoma (continued). "Since MMP‐1 and MMP‐9 have been reported to play crucial roles in breast cancer, the activities of MMP‐1 and MMP‐9 in spheroid‐conditioned media were also analyzed." (PMID 35600659, 2022). "Higher MMP1, SDC1, SPP1, and CD24 expression was correlated with worse overall survival (OS) and relapse-free survival (RFS) in breast cancer patients." (PMID 35037689, 2022). "MMP1 and MMP9 can be used as independent prognostic factors to predict the prognosis of breast cancer patients, in order to further study the pathological mechanism and possible treatment targets for breast cancer, especially for Her2 and Basel subtypes." (PMID 35069702, 2021). "DBD-CAP was shown to affect also the proteolytic potential of tumor cells since it significantly down-regulated the expression of MMP-1, MT1-MMP and uPA in the metastatic ER- breast cancer cells." (PMID 35111687, 2021). "MMP1 and PAR1 were co-expressed in gall bladder cancer, breast cancer, prostate cancer, and liver cancer." (PMID 34753916, 2021). "Inhibition of either MMP-1 or PAR1 significantly decreases tumor growth, implicating CAF-secreted MMP-1 and PAR1-mediated Ca2+ influx in breast cancer progression." (PMID 34768796, 2021). "Our results show higher immunohistochemical expression levels for MMP1 intensity and MMP-3 percentage and intensity for early-stage breast cancer (EI, EII)." (PMID 34445715, 2021). "A previous study showed that PLAU1, MMP1, and MMP2 are involved in signaling pathways related to invasion in breast cancer." (PMID 33816223, 2021). "We investigated MMP1 and MMP11 expression in PBMC from breast cancer patients and we analyzed gene expression changes upon their interaction with cancer cells and cancer-associated fibroblasts (CAF)." (PMID 33396463, 2020). "In the present study, we have investigated MMP1 and MMP11 gene expression in PBMC because of their relationship with lymph node metastasis and hematogenous metastasis in breast cancer, respectively." (PMID 33396463, 2020). "In the present work, we have investigated the gene expression of MMP1 and MMP11 in PBMC from breast cancer patients (BC-PBMC), before and after co-culture with breast cancer cell lines or CAF, compared to PBMC from healthy women (C-PBMC)." (PMID 33396463, 2020). "Basal gene expression of MMP1 and MMP11 was studied in PBMC from breast cancer patients (BC-PBMC) and healthy women (controls, C-PBMC)." (PMID 33396463, 2020). "PBMC from patients or controls showed increased MMP1 gene expression after co-culture with MCF-7 and MDA-MB-231 breast cancer cell lines, although differences were only statistically significant for C-PBMC." (PMID 33396463, 2020). "Up-regulated expression of COL10A1, MMP11, CST1, GJB2, MMP1, MMP13, and CEACAM6; down-regulated expression of ADH1B, CIDEC, THRSP, GPD1, TIMP4, FABP4, and SCARA5 genes was common in breast cancers of the two populations." (PMID 31292488, 2019). "Overexpressing LPP1 also decreased mRNA levels of MMP-1, MMP-3 and MMP-13 in BT-549 breast cancer cells and 4T1 mouse breast cancer cells." (PMID 31534541, 2019). "In particular, miR-21, MMP1, MMP9, MMP13, CXCR4 and vimentin were found overexpressed in the invasive margins of breast cancer tissues of clinical samples and in the cancer cell lines; E-Cadherin, on the other hand, was decreased." (PMID 31362429, 2019). "QPCR analysis confirmed the up-regulated expression of MMP1, MMP13, and MMP11 genes and down-regulated expression of ADAMTS1 and ADAMTS5 genes in breast cancers observed in the microarray experiments." (PMID 31292488, 2019). "Matrix metalloproteinase-1 (MMP-1), matrix metalloproteinase-2 (MMP-2), cyclooxygenase-2 (COX-2), and epiregulin (EREG) synergistically promote breast carcinoma intravasation by stimulating neoangiogenesis and leaky blood vessel formation." (PMID 31817450, 2019). "Summing up, luteolin and apigenin inhibited pro-intravasative mechanisms in MDA-MB231 breast cancer cells at the levels of CYP1A1 activity and MMP1 expression." (PMID 29593542, 2018).
breast carcinoma (continued). "MMP1, a member of the MMP family that is an inducer of ECM degradation, was highly expressed in breast cancer stroma." (PMID 30237810, 2018). "In particular, collagenase MMP-1 that can degrade type I, II, and III collagens is highly expressed and metastatic in breast cancer." (PMID 30065181, 2018). "In the tumor microenvironment, cancer cells coexist with preosteoclasts and release many soluble factors such as IL8, IL11, MMP1, MMP2, TNFα, and PGE2, which determine the direct osteolytic capability of breast cancer cells." (PMID 30126457, 2018). "MMP1, a collagenase that cleaves collagen Type I, II, III, VII and X, is overexpressed in a variety of cancers types including breast cancer and in circulating cancer cells." (PMID 30514916, 2018). "Slug directly promotes MMP1 transcription, which is a previously unrecognized mechanism of MMP1 upregulation in MDR breast cancer cells." (PMID 28334049, 2017). "In this study, we further investigated the functional role of MMP1 and how it is upregulated in multi-drug resistant (MDR) breast cancer cells." (PMID 28334049, 2017). "In other animal models, fibroblast-derived MMP-1 activates the PAR-1 receptor, resulting in tumor invasion and angiogenesis in breast cancer." (PMID 28966935, 2017). "The present study mainly focused on the analysis of synergistic effects of three functional SNPs of MMP1 (rs1799750) -1607 1G/2G, MMP3 (rs35068180) -1171 5A/6A and MMP9 (rs3918242) -1562 C/T genes in relation to breast cancer development and progression." (PMID 28961241, 2017). "MMP1 cleaves and activates protease-activated receptor-1 (PAR-1), leading to increased migration and invasion of breast cancer cells." (PMID 29142217, 2017). "Functional studies showed that overexpression of miR-361-5p suppressed the glycolysis and proliferation of breast cancer cells by targeting FGFR1, the invasion and metastasis by targeting MMP-1." (PMID 29132384, 2017). "The dimerization of HER3 and HER2 synergistically increases heregulin-β1-induced MMP-1 and MMP-9 expression in breast cancer cells." (PMID 28881584, 2017). "In breast cancer, cell division cycle 25A (CDC25A) mediates metastasis by regulating MMP1 through FOXO1." (PMID 27486383, 2016). "Several top up-regulated genes were associated with motility, adhesion, invasiveness, and metastasis in breast cancer or other cancers, such as GBP1, ITGB6, ITGA2, and matrix metalloproteases MMP10 and MMP1." (PMID 27351228, 2016). "We showed that in the ER+ breast cancer cell line T47D, knocking down RKIP expression increased cancer cell invasion in vitro by increasing the expression of MMP1 and MMP2." (PMID 26308852, 2015). "High expression of MMP-1 (P=0.00012), and MMP-9 (P=0.00022) is predictive of lower RFS in endocrine treated ER+ human breast cancer patients." (PMID 28721370, 2015). "In this study we found that Pit-1 regulated MMP-1 and MMP-13 in breast cancer cells at transcriptional level." (PMID 25527274, 2014). "Our data indicates that Pit-1 regulates MMP-1 and MMP-13, and that inhibition of MMP-13 blocked invasiveness to lung in Pit-1-overexpressed breast cancer cells." (PMID 25527274, 2014). "MDA-MB231 breast cancer cells were treated with culture media of MDA-MB231 and normal HDFs for 24 h, and cell lysates were harvested for detecting the level of MMP-1, -2 and -9 mRNA expression." (PMID 25013462, 2014). "Among these, MMP-1, 2, 9, 11, TIMP-1, 2 levels have been largely investigated in breast carcinoma tissues." (PMID 25510449, 2014). "In this study we evaluate the relationship between Pit-1 and two collagenases: matrix metalloproteinase-1 (MMP-1) and matrix metalloproteinase-13 (MMP-13), which have been related to metastasis in breast cancer." (PMID 25527274, 2014). "To assess the tumorigenic potential of PTK7 in BC and LN we compared the PTK7 expression level and co-expression with other breast cancer related genes (HER2, HER3, PAI1, MMP1, CK19, CD44)." (PMID 24409301, 2014).
breast carcinoma (continued). "MMP-1, ADAMTS1, OPN, and PTHrP were up-regulated in MDA-231BO2 breast cancer cells upon RANKL stimulus." (PMID 23696795, 2013). "In prostate and breast cancer, RANKL induced cell motility through MMP-1 up-regulation, whereas thromboxane A-enhanced lung cancer migration was shown to involve MMP-1 expression." (PMID 23892595, 2013). "In previous reports we analyzed the expression of several MMPs and TIMPs (MMP-1, 2, 7, 9, 11, 13 and 14, and TIMP-1, 2 and 3), either at the invasive front or at the tumor center of breast carcinomas, in many of the women included in the present study." (PMID 23300781, 2012). "The results demonstrated that active MMP-1 proteolysed latent TGFα to generate active TGFα, leading to an activated EGFR signal pathway, thus linking MMP-1 and the EGFR signaling pathway in metastatic breast cancer cells." (PMID 23217186, 2012). "Together, these results provide a rationale for targeting EGF-like factors (HB-EGF, AREG and TGF-α) and proteases (MMP1 and ADAMTS1) in tumour cells, as well as EGFR in osteoblasts for controlling osteolytic bone metastasis of breast cancer." (PMID 20010942, 2010). "Median plasma MMP1 levels were significantly higher (p = 0.0005) in healthy controls (3.45 ng/ml, interquartile range IQR 2.42–4.17 ng/ml) than in breast cancer patients (2.01 ng/ml, IQR 0.79 – 3.71 ng/ml)." (PMID 18366705, 2008). "In summary, we observed differences in MMP1 and MMP8 plasma levels between healthy controls and breast cancer patients as well as between breast cancer patients." (PMID 18366705, 2008). "Recently, we reported the clinical value of this technology to evaluate the expression of MMP-1, -2, -7, -9, -11, -13 and –14, and TIMP-1, -2 and 3, in breast cancer." (PMID 17848954, 2007). "We utilised the unique in situ-reverse transcription-polymerase chain reaction (IS-RT-PCR) methodology to localise the in vitro and in vivo gene expression of MT1-MMP, MMP-1 and MMP-3 in human breast cancer." (PMID 16430785, 2006). "Furthermore, SDC3 depletion significantly upregulated MMP1, and downregulated MMP9 in MDA-MB-231 cells, suggesting a multifunctional role of the molecule in modulating migration and invasion in breast cancer." (PMID 41148827, 2025). "The identification of IL-11, as well as of MMP-1 and MMP-13, which are also mediators of breast cancer metastasis to the bone, supports the hypothesis that PKD2 and PKD3 contribute, via the secretome, to the colonization of the bone in TNBC." (PMID 38323010, 2024). "Moreover, immunohistochemical staining of breast cancer tissues revealed a positive correlation between PRDX3 and MMP-1 expression in both epithelial and stromal parts of the tissues." (PMID 38321552, 2024). "Studies have shown that CAF-derived MMP-1 and MMP-9 promote the invasion of breast cancer cells." (PMID 37496657, 2023). "For the matrix degradome, MMP1, MMP2, MMP10 and MMP14 showed trends of progressive upregulation with increasing metastatic potential in lung fibroblasts exposed to secreted factors from breast cancer cells." (PMID 37903851, 2023). "Due to their solid digesting function, the matrix metalloproteases MMP1, MMP11, MMP14, and MMP16 might confer invasiveness to breast cancer cells through the Zn2+-bound ZEB1." (PMID 36910659, 2023). "Because hydroxyapatite upregulates the expression of matrix metalloproteinase 1 (MMP-1) and promotes the migration of breast cancer cells through decreased elasticity of the extracellular matrix, augmented gene expression of MMP-1 predicts worse metastasis-free survival." (PMID 36513704, 2022). "Notably, similar to MMP-1, these studies showed that tumoral MMP-2 promotes breast cancer metastasis to the brain." (PMID 36741729, 2022).
breast carcinoma (continued). "Furthermore, we showed that proteins from the matrissome, such as MMP1 and CTGF, were also increased in our microfluidic platform, consistent with an increased breast cancer aggressive behavior." (PMID 35243294, 2022). "MMP-1 and MMP-3 are involved in the maintenance of the angiogenic phenotype; thus, inhibition of these proteinases may be of value both in preventing breast cancer and in blocking metastasis of established tumors." (PMID 34445715, 2021). "Through gain and loss of function and rescue experiments, we confirm that MIR200CHG regulates the expression of tumor-associated proteins CDKN2A, cyclin D1, cyclin E1, BCL2, BAX, MMP1, MMP2, and MRP1 by binding YB-1, thereby promoting breast cancer proliferation, invasion, and resistance." (PMID 34272387, 2021). "Also, gene expression of MMP1 and MMP11 increases in PBMC after co-culture with breast cancer cell lines, NF or CAF." (PMID 33396463, 2020). "We found that miR-101-3p expression is lost in brain metastatic breast cancer cells, while ectopic expression of miR-101-3p reduces transmigration of cancer cells through the brain endothelium through reduction of COX-2/MMP1 expression which interferes with the inter-endothelial junctions." (PMID 32645833, 2020). "Notably, elevated HO1 activity induced matrix metalloproteinase 1 (MMP1) and stimulated migration and invasion in human breast cancer cells." (PMID 33287315, 2020). "Gene expression of MMP1 and MMP11 in PBMC from breast cancer patients (n = 54) and control (n = 28); expression of IL1A, IL6, IL17, IFNβ, and NFĸB in breast cancer cell lines (MCF-7 and MDA-MB-231); and, additionally, IL10 and MMP11 in CAF and NF were analyzed by qRT-PCR before and after co-culture." (PMID 33396463, 2020). "Our results show that restoring miR-101-3p expression in BC cells reduces transmigration of breast cancer cells through the brain endothelium by downregulating COX-2/MMP1 signaling, however without clear effect on HBEGF and ST6AGLNAC5 expression." (PMID 32645833, 2020). "We used the STRING bioinformatic tool to find biological processes associated with the gene products that we analyzed for their prognostic impact on breast cancer, namely IKKα (CHUK), IKBKB, p50/NFKB1, p65/RELA, NIK (MAP4K4), p52 (NFKB2), RELB, IL-8 (CXCL8), IL6, and MMP-1." (PMID 31602271, 2019). "In addition, it was reported that matrix metalloproteinase-1 (MMP-1) is induced by FOXO1 and enhances the invasive potential of human breast cancer cells." (PMID 31823759, 2019). "We observed an association of IL-8 and MMP-1 expression with poor RFS and OS in breast cancer patients, regardless of ER or nodal status or molecular classification." (PMID 31602271, 2019). "MMP-1, MMP-2, MMP-9 and MMP-14 promote breast cancer growth and metastasis." (PMID 30237810, 2018). "Importantly, MMP1 and VCAM1 expression in part constitute a profile of invasive breast cancer cells." (PMID 29735912, 2018). "Stromal-derived MMP-1 have been shown to cleave and activate G-protein-coupled receptor PAR1, leading to the activation of intracellular signals regulating the invasion process in breast cancer cells." (PMID 30026761, 2018). "In addition, high expression of FOSL1 caused by rearrangement of the chromosome band at 11q12 appeared to be associated with desmoplastic fibroblastoma and directly induced MMP-1 and MMP-9 promoter activity in breast cancer progression." (PMID 28049150, 2017). "The results showed that high MMP1 expression is associated with significantly worse OS and RFS no matter in all breast cancer patients or only in ER+ breast cancer patients." (PMID 28334049, 2017). "However, the levels of Survivin and MMP-1 were upregulated in FRK knockdown SKBR3 and MCF-7 breast cancer cells." (PMID 29348886, 2017). "In addition, we demonstrated that Slug directly promotes MMP1 transcription, which is a previously unrecognized mechanism of MMP1 upregulation in MDR breast cancer cells." (PMID 28334049, 2017).